IFNG (interferon gamma)
Diseases named in the same sentence as IFNG in open-access papers (continued):
Sharing a sentence is not in itself a finding about the gene and the disease.
cancer (continued). "JAK1 is a critical molecule linking IFNγ receptor activation to activation of all IFNγ-sensitive genes and loss of JAK1 downregulates class II, class I, and CXCL9/10 in cancer cells." (PMID 37565053, 2023). "Treatment with the class I HDAC inhibitor entinostat and IFNγ increased class II expression to 65.1% of cancer cells at 72 hours in 658 and doubled the effect of GSK126 at 24 hours." (PMID 37565053, 2023). "The microenvironment surrounding the emerging cancer cells is initially restrictive in general, owing to the presence of Th1 type cytokines such as interferon gamma (IFNγ) and granulocyte macrophage colony-stimulating factor (GM-CSF)." (PMID 36765912, 2023). "These cells are able to attack cancer cells via the release of the cytolytic content of their granules such as perforin (Pr), granzymes (Gzs), and interferon-gamma (IFN-γ) into the cytosol of targeted cells, leading to lysis of target cancer cells." (PMID 37580655, 2023). "These cells are loaded with direct cytotoxic mediators, including granzymes, perforin, interferon gamma (IFNγ), and Fas Ligand, that allow them to serially kill cancer cells displaying cognate antigens within only few minutes of interaction." (PMID 37081897, 2023). "Continuous interferon-gamma exposure can lead to immunoediting of cancer cells, resulting in immune escape." (PMID 37100920, 2023). "In cancer patients, an increase in IFNγ expression and IFNγ-related transcriptomic profile predicts the response to anti-PD-1 therapy." (PMID 37189417, 2023). "IFNγ promotes the anti-cancer efficacy of PD-1 blockade in preclinical models including pancreatic cancer, which is generally resistant to anti-PD-1 therapy." (PMID 37189417, 2023). "The inactivation of IFNγ signal pathway is the key for cancer cells to escape CAR-T cell killing, T cell killing, and ICB therapy." (PMID 37427373, 2023). "At visit 2, 85% (45 of 53 participants) of all individuals with cancer had an increase in the frequency of Delta spike-specific IFNγ-secreting T cells compared to prevaccination levels." (PMID 36543907, 2023). "Yet, the importance of CD4+ T cells in cancer elimination via secretion of effector cytokines such as interferon-γ (IFNγ) and tumor necrosis factor-α (TNFα) has also been reported." (PMID 39086686, 2023). "Firstly, T cell-inflamed GEP score was used to predict potential in cancer immunotherapy, Th1/IFNγ gene signature (a cytokine with a key function in immune regulation and anticancer immunity) and CYT score to reflect cytotoxic effect were higher in C1." (PMID 38025763, 2023). "Cancer cells cultured with macrophage activation factors (IFNγ/Pam3SCK4, or IL-4) change their chemokine profile." (PMID 37445941, 2023). "With respect to quantification of pro-tumoral effects of IFNG, it is currently unclear what is the relative importance of various T cell exhaustion markers that limit the immune response against cancer." (PMID 37182110, 2023). "Cancer cells have evolved an innate program to respond to different cytokine stimuli (Ifnγ, IL-27, or IL-1) by upregulating both IDO1 and PD-L1 to promote cancer cell survival." (PMID 37985999, 2023). "GSEA demonstrates that low-risk BRCA patients are related to “Cancer immunotherapy by PD1 blockade,” “ESR mediated signaling,” “Estrogen dependent gene expression,” and “Interferon gamma signaling,” while high-risk BRCA patients are related to “Cell cycle”." (PMID 37443486, 2023). "CD96 is commonly expressed on the surface of CD8+ T cells and NK cells and has been implicated as an immune checkpoint inhibitor capable of suppressing IFNG production as well as cytotoxicity and worsening patient prognosis in cancer." (PMID 37177979, 2023). "Cancer cells have learned to co-opt this protective mechanism as a means of counteracting immunosurveillance, as they can upregulate PD-L1 in response to IFNγ exposure." (PMID 37762241, 2023).
cancer (continued). "In view of these findings, IFNγ is considered the key mediator of the anti-cancer activity triggered by IL12." (PMID 36839699, 2023). "Together, these results show that endogenous DUX4 expression in 2 independent cell types, FSHD muscle cells and SuSa germinoma cells, suppress protein synthesis and that this correlates with suppression of IFNγ-induced MHC-I expression in cancer cells." (PMID 37747887, 2023). "PDL1 expression is induced by IFNγ (secreted by activated NK and T cells), and is abundant in carcinomas and TME." (PMID 37100920, 2023). "The EBVaGC carcinoma cells also exhibited significant differences in gene expression, with higher levels of interferon-gamma (IFN-γ)-induced genes, including MHC class II genes compared to EBVnGC." (PMID 37370788, 2023). "Interferon alpha response and interferon gamma response pathways exhibited consistently positively correlated with TRIMs scores across cancer types." (PMID 36461099, 2022). "The effector functions of interferon gamma play a significant role in cancer immunoediting and natural killer cell activation." (PMID 36518665, 2022). "In particular, the ability of IFNγ to promote the expression of PD ligand 1 (PD-L1) in cancer cells is considered evidence that it also has immunosuppressive properties." (PMID 36428508, 2022). "It has been reported that immunotherapy-activated CTLs release interferon-gamma (IFN-γ) which suppresses xCT expression in cancer cells promoting ferroptosis." (PMID 36338517, 2022). "This was consistent with the functional cytokine level (i.e., IFNγ), which was responsible for killing the cancer cells." (PMID 36059807, 2022). "Type 1 interferons including IFN alpha and beta and interferon gamma have pivotal roles in cancer immunosurveillance and priming of T cells in tumors." (PMID 36518665, 2022). "This likely reflects the “hotter” TME of HPV+ CC since, like other virus-induced cancers, they exhibit increased levels of IFNγ, as well as higher MHC class I and II expression." (PMID 36497170, 2022). "In agreement with the previous studies, SZU251 + MUC1 caused a rapid induction of common cytokines such as IL6, TNFα and IFNγ in mouse BMDCs and spleen lymphocytes in vitro, favoring Th1-mediated immune responses and cytotoxic T cells acting on cancer cells." (PMID 36499455, 2022). "Interferon-gamma (IFN-gamma) stimulation is another mechanism by which MHC expression can be increased in cancer cells." (PMID 36344500, 2022). "NK cell receptor expression, downstream phosphorylated targets, and IFNγ production were assessed using peripheral blood mononuclear cells (PBMCs) from patients undergoing cancer surgery." (PMID 36498937, 2022). "Further analysis using a published IFNγ gene signature revealed striking variation by cancer type and MSI status." (PMID 35262923, 2022). "Fibrocytes secrete only IL23 and IFNγ, which were suppressed upon co-culture, whereas cancer cells or fibrocytes secrete CCL5, IL-1ra, CD54, CXCL10, MIF, CXCL1, IL-6, and IL-8, which was not affected by co-culture." (PMID 36241617, 2022). "Interferon gamma levels, a key indicator of antitumor activity, revealed a significant difference between the A549 cancer cell lines co-cultured with PBMCs containing the naïve and activated T-cells (p < 0.0001)." (PMID 35454072, 2022). "Interferon-γ (IFNγ) is a cytokine with limited evidence of benefit in cancer clinical trials to date." (PMID 35459800, 2022). "Activated T cells infiltrating the tumour microenvironment secrete interferon-γ (IFNγ) that induces expression of the enzyme IDO1 in cancer cells." (PMID 35264796, 2022). "Blocking these molecules by ICIs allows eliminating local suppression and inducing cancer-cell killing by CD8 positive T cells producing interferon gamma (IFN-γ) and tumor necrosis factor α (TNF-α)." (PMID 36533080, 2022).
cancer (continued). "While IFNγ is classically reported as an anticancer cytokine, it was also reported to have a protective role for cancer in the context of radiation-induced genotoxicity." (PMID 35089788, 2022). "Cancer cells express higher levels of immunosuppressive molecules after interferon gamma (IFN-γ) induction and then escape immune elimination." (PMID 35464451, 2022). "The connections of TNFα, IL-1β and IFNγ with the PD-L1/PD-1 axis, as well as with cancer-related inflammation, have led us to characterize the impact of these cytokines—each alone and in different combinations—on the expression of PD-L1 by TNBC cells." (PMID 35884574, 2022). "TRP score was positively associated with malignant pathways in pan-cancer, such as IL6–JAK–STAT3 signalling, interferon-gamma response, and inflammatory response." (PMID 35493463, 2022). "They found a significant decrease in CD212 expression and impaired IFNγ production up to POD7 in non-cancer surgery patients." (PMID 36498937, 2022). "We found that EMT, interferon alpha response and interferon gamma response were consistently correlated with TRIMs scores across cancer types." (PMID 36461099, 2022). "Mechanistically, BAY1082439 converts cancer cell-intrinsic immune-suppression to immune-stimulation by promoting IFNα/IFNγ pathway activation, β2-microglubin expression and CXCL10/CCL5 secretion." (PMID 35013322, 2022). "IFNγ released by immune cells can trigger cancer immunosuppression against CD8+ T cell activation and effector function via activating JAK-STAT signal to induce the up-regulation of PD-L1." (PMID 35185580, 2022). "Upon exposure to IFNγ present in the microenvironment, cancer cells increase the expression of PD-L1, which interacts with PD-1 expressed on T cells and inhibits the antitumor immune response." (PMID 35656514, 2022). "IL-12 has been demonstrated to regulate both innate and adaptive immunities in cancer therapy, and IFNγ drives PD-L1 expression, which correlates to clinical responses to anti-PD-1 and anti-PD-L1 antibody therapy." (PMID 36582243, 2022). "Many cancer immunotherapies, including checkpoint inhibitors, induce IFNγ production by various immune cells, especially activated T cells and NK cells." (PMID 36551577, 2022). "IFNγ, in turn, has cytostatic and pro-apoptotic functions and is useful for adjuvant immunotherapy for different types of cancer, as it can stimulate an anti-tumour immune response." (PMID 36678733, 2022). "We observed that the TRP score was positively associated with many malignant pathways in pan-cancer, such as IL6–JAK–STAT3 signalling, interferon-gamma response, and inflammatory response." (PMID 35493463, 2022). "Given the importance of CD8+ T cells as effectors for eliminating cancer cells, we evaluated the co-expression of IFNγ and GZMb in CD8+ TILs—two commonly used markers to indicate their activation status and antitumoral activities." (PMID 35347124, 2022). "The analysis by ELISA of the CIK-conditioned medium, always collected at the end of 72 h cancer cell killing assays (n = 6), confirmed an intense production of protease granzyme B along with IFNα and IFNγ." (PMID 36142281, 2022). "We observed that the AP3S1 overexpression was positively associated with many malignant pathways in pan-cancer, such as IL6 JAK STAT3 signaling, IL2 STAT5 signaling, TGF BETA signaling, interferon gamma response, and interferon alpha response." (PMID 35874816, 2022). "These immune cells, as anti-cancer immune cells, release cytokines such as interferon-gamma (IFN-γ) and tumor necrosis factor (TNF)-alpha which are major effectors upregulating HLA class I molecules." (PMID 36437379, 2022). "Substantial evidence has highlighted IFNγ response and antigen presentation as key components for cancer immunosurveillance and immunotherapy." (PMID 35982220, 2022).
cancer (continued). "The T-cell repertoire of cancer patients was skewed towards differentiated phenotypes expressing IFNγ but even more pronounced towards IL-17 production both in healthy donors and cancer patients." (PMID 36139625, 2022). "Together, our sequential screens identified matched roles for IFNγ and type I PRMTs in modulating positively and negatively (respectively) the emergence of cancer persisters." (PMID 35089788, 2022). "The ability of IMC-KRASG12D to specifically mediate T cell activation and redirect T cell killing of cancer cells expressing natural KRASG12D was determined using IFNγ ELISPOT assays and a quantitative live cell imaging assay." (PMID 36088370, 2022). "In comparison with cancer cells in the GG components, downregulated pathways include interferon gamma signaling pathway, surfactant metabolism, and lysosome-related pathway." (PMID 35874770, 2022). "Instead, the B-MF transfer significantly decreased the frequency and numbers of IFNγ-expressing CD4+ T cells in both cancer models." (PMID 36104343, 2022). "BEBT-908, a dual PI3K/HDAC inhibitor, induces ferroptosis resulting in increased MCH-1 expression and activation of STAT1/IFNγ signaling in cancer cells, which in turn promotes antitumor immunotherapy." (PMID 36289191, 2022). "Interferon γ (IFNγ), an important inflammatory factor released by effector T cells in the process of killing tumors, triggers cancer cell immunosuppression against CD8+ T cells surveillance via activating JAK-STAT pathway to induce the up-regulation of PD-L1." (PMID 35185580, 2022). "Expression of Granzyme B and perforin and incretion of IFNγ of DNT cells were also involved in the cytotoxicity to cancer cells, which is a classical method to exert antitumor efficacy." (PMID 35894707, 2022). "IFNγ scores were positively correlated with catabolism or putrescine scores in four cancer types, respectively." (PMID 36052016, 2022). "IFNγ secreted by T cells further activate PDL-1 expression in the cancer cells, which pave the way for anti-PD-1 therapy." (PMID 35013322, 2022). "IFNγ was decreased in stromal cancer cell patients, but IFNγ producing cell subsets increased significantly after IFNα treatment." (PMID 35242139, 2022). "IFNγ was first identified as a cytokine that evoked an immune response to viral infection and played an important role in cancer immunity." (PMID 35053427, 2022). "Th1 cell IFNγ production is also regulated by signaling factors and immunosuppressive immune cells in the cancer microenvironment." (PMID 34385592, 2022). "Genomically, a characteristic of the IFNγ-signaturehigh basal/squamous subgroup is that the cancers carry elevated signatures of Apolipoprotein B mRNA Editing Catalytic Polypeptide-like (APOBEC) mediated mutagenesis." (PMID 36358715, 2022). "This ability of HPAF-II cells to inhibit T-cell proliferation and IFNγ/GMCSF release was fully reversed upon pretreatment of the cancer cells with RXC004." (PMID 36922934, 2022). "Based on its pro-apoptotic and anti-proliferative functions, IFNγ is considered to have potential adjuvant immunotherapeutic effects on different types of cancer." (PMID 34976218, 2022). "Studies have found that a variety of cancer cell types upregulate PD-L1 in response to interferon gamma (IFNγ) as well as other oncogenic signaling pathways." (PMID 35336018, 2022). "In cancers IFNγ mainly has antitumor effects, with cytostatic, pro-apoptotic, antiproliferative, and antiangiogenetic functions, and can induce Treg apoptosis." (PMID 35806366, 2022). "The low-risk group had higher IFNG, higher MSI score, and lower cancer CAFs amount, which showed that the immune landscape of the low-risk group was more active." (PMID 35495147, 2022). "Accordingly, Tc1 cells capable of producing IFNγ are a major immunological effector cell population mediating resistance to cancer." (PMID 35053375, 2022). "Taken together, we concluded that cancers generate B-MF mostly to downregulate anticancer IFNγ+CD4+ T cells." (PMID 36104343, 2022).
cancer (continued). "The dual inhibition sustained an increased production of IFNγ, TNFα, IL-12 and IL-6 by PBMCs, that contribute to expression of Ido-1 on cancer cells." (PMID 36419183, 2022). "NK cells and T cells appear to secrete IFNγ, which induces the expression of PD-L1 on the surface of target cells, including cancer cells." (PMID 35326729, 2022). "One study showed that in 21 cancer patients, administration of rhIL-12 once a week increased the expression of IFNγ, even at very low doses." (PMID 36203573, 2022). "By provoking inflammation, BCG can lead to the production of a factor called “interferon gamma” and an immune response that can eliminate the cancer." (PMID 36358715, 2022). "Previous reports showed that PD-L1 can be induced in MDS cells by IFNγ and TNFα, although a variety of other factors (i.e., IL-10, FasL, and IL-17A) have been shown to upregulate PD-L1 in other cancer types." (PMID 35992887, 2022). "In terms of the 50 cancer hallmarks, interferon-gamma response, inflammatory response, E2F-targets, etc., were significantly upregulated in the CAPN8-high group, while the oxidative phosphorylation pathway was slightly downregulated." (PMID 36389799, 2022). "The correlation change network of GO term interferon-gamma production gives a reasonable representation of the biological mechanisms of cancer progression." (PMID 35610556, 2022). "In contrast, IL12 and IFNγ signaling was attenuated in Tyk2Δ/Δ tumors, resulting in impaired cancer immune surveillance with reduced NK cell and T cell infiltration." (PMID 36185806, 2022). "Here, we review recent advances showing that the adhesion between CAR T cells and cancer cells from solid tumors strengthens over time in an IFNγ- and ICAM-1-dependent manner, resulting in CAR T cell-mediated killing." (PMID 36189315, 2022). "ACE-oNK-HER2 effectively eliminated HER2-expressing cancer cells at a relatively low E:T ratio and increased secretion of IFNγ." (PMID 34072864, 2021). "The memory-like NK cells derived from haplo-HSCT donors or from cancer patients were evaluated for their capacity to secrete IFNγ in comparison with the control NK cells." (PMID 33808051, 2021). "Upon encountering the cancer cells, cytotoxic T cells further proliferate and exhibit an enhanced level of activity by producing IL-2 and IFNγ, while regulatory T cells negatively modulate their activity by inducing their exhaustion." (PMID 34359653, 2021). "Cancer cells were also treated with IFNγ 48 hr prior to co-culture with the respective TCR-modified PBMCs." (PMID 33875134, 2021). "It is well documented that IFNγ, which is secreted by immune cells, such as T cells, is critically important for the inhibition of cancer cell growth." (PMID 34709754, 2021). "Many immunotherapeutic drugs including CTLA-4 and PD-1 inhibitors eliminate cancer cells by increasing IFNγ expression." (PMID 34248641, 2021). "A major cancer cell resistance mechanism involves lesions in genes in the interferon-gamma (IFNγ) signaling pathway or antigen presentation machinery that independently impair the efficacy of immunotherapy." (PMID 33403469, 2021). "Our recent study showed that genetic engineering of PD-L1 and PD-L2 on cancer cells via CRISPR/Cas9 approaches can improve IFNγ secretion by CD8+ T cells." (PMID 33557054, 2021). "We designed and for the first time tested the cancer cell spheroid-based model for SFV vector delivery of IFNg, as well as its ability to activate macrophages under free-floating conditions." (PMID 34835178, 2021). "Effector CD8+ T cells released cytokines IFNγ, and both of them were key features of effective immunotherapy in cancer patients." (PMID 34868393, 2021). "EZH2-mediated histone methylation represses NLRC5 in stem cells and cancer cells, whereas IFNγ promotes the same events in macrophages on certain genes." (PMID 33671123, 2021). "In 1998, a study showed that immune surveillance against cancer cells was affected by the interferon gamma pathway." (PMID 34072037, 2021).